IL6 (interleukin 6)
Diseases named in the same sentence as IL6 in open-access papers (continued):
Sharing a sentence is not in itself a finding about the gene and the disease.
Acute hepatitis (6 papers, 2013 to 2023). Acute hepatic injury resulting from inflammation typically accompanied by increased serum alanine transaminase activity. "IκBζ-dependent genes include IL-6 and lipocalin-2 that contribute to controlling acute hepatitis and bacterial infection." (PMID 36978599, 2023). "As plant lectin concanavalin A (ConA) is another widely used mouse model for introducing immune-mediated acute hepatitis by inducing TNFα, IL-6 and IFNγ, we further detected the role of Bcl-3 in ConA-induced liver injury." (PMID 34853447, 2022). "The transcript level of TNF-α, TRAIL, IL-1β and IL-6 was significantly up-regulated following D-GalN Poly(I:C) induced acute hepatitis (8h) compared to D-GalN or PBS control mice." (PMID 24058536, 2013). "Our results are consistent with those of recent reports showing that the inhibition of the enzymatic activity of IDO significantly exacerbated liver injury in α-galactosylceramide (α-GalCer)- and CCl4-induced acute hepatitis animal models via the upregulation of IL-6 and TNF-α." (PMID 24039933, 2013). "LY294002 is a pan-PI3K inhibitor, which was proven to inhibit LPS-induced acute hepatitis injury in a murine model and also reduced TNF-α and IL-6 expression." (PMID 36558058, 2022).
Adrenal insufficiency (6 papers, 2016 to 2025). Insufficient production of steroid hormones (primarily cortisol) by the adrenal glands. "Ganguli and colleagues observed that the presence of age-related adrenal insufficiency; the overexpression of some cytokines, including interleukin-6 (that was associated with increased vasopressin secretion); or simply poor solute intake are relevant risk factors in the elderly." (PMID 40729144, 2024). "Secondary adrenal insufficiency impairs cortisol-mediated suppression of inflammatory cytokines and immune regulation, allowing IL-6 and TNF-α to remain elevated, further accelerating skeletal muscle protein breakdown." (PMID 41181767, 2025). "The primary and secondary adrenal insufficiency may be attenuated by increased circulating IL-6 and impaired cortisol metabolism." (PMID 27242936, 2016). "In contrast, SF1CreSRBIfl/fl littermates showed adrenal insufficiency, with no iGC production and uncontrolled IL-6 in circulation." (PMID 40048257, 2025).
amoebiasis (6 papers, 2014 to 2026). "In a mouse model of amebiasis, IL-6 deficiency increased the susceptibility to ALA, suggesting a relevant role for IL-6 in the inflammatory processes induced by E. histolytica." (PMID 25420932, 2014). "Most recently, it was shown that E. histolytica possesses a human-like macrophage migration inhibitory factor (EhMIF) that induces the production of IL-6 that might further contribute to IL-6 production during invasive amebiasis." (PMID 25420932, 2014). "Within the biological process of amoebiasis, dietary supplementation with PPAH decreased the expression of several genes, including Il6, Serpinb9c, Rab5a, Muc2, Rab7, Lamb1, and Lama1." (PMID 39591294, 2024).
aortitis (6 papers, 2019 to 2024). Inflammation of the aorta. "Tocilizumab (162 mg subcutaneous weekly), an interleukin-6 inhibitor, was successfully proven to be effective in GCA and is available in the UK for use in aortitis in ‘relapsing and refractory cases’, following the failure of two conventional treatment strategies." (PMID 39728295, 2024). "Additionally, G-CSF-induced autoimmune reactions mediated via IL-6 between Th17 cells and CD4+ T cells is also thought to result in aortitis, aneurysm or dissection." (PMID 33122662, 2020). "It was reported that the development of aortitis was diminished in Il1r1−/−Il1rn−/− mice and Tnfa−/−Il1rn−/− mice, whereas it was normal in Il6−/−Il1rn−/− mice, indicating that IL-1α and/or IL-1β, and TNF are crucial for development of aortitis in Il1rn−/− mice." (PMID 31745167, 2019). "On the other hand, our results suggest that IL-25 may enhance production of IL-6, IL-17A and TNF, but not IL-23, thereby contributing to development of IL-1–, TNF– and IL-17A–dependent aortitis in Il1rn−/− mice." (PMID 31745167, 2019).
aseptic meningitis (6 papers, 2012 to 2025). Inflammation of the membranes surrounding the brain and spinal cord without a bacterial pathogen. "Serum IL-6 has been reported to be strongly associated with aseptic meningitis among children with EV-A71-induced HFMD." (PMID 34809671, 2021). "Patients 10 and 33 presented with aseptic meningitis, with patient 10 showing elevated IL-6 in the cerebrospinal fluid." (PMID 40574834, 2025). "Interleukin-6 (IL-6) activity and tumor necrosis factor-alpha concentrations in the cerebrospinal fluid (CSF) of patients with bacterial or viral, aseptic meningitis is useful for different type of infections." (PMID 23483792, 2012). "Moreover, mean IL6 CSF in children with aseptic meningitis is higher than in patient with normal CSF." (PMID 23483792, 2012). "A potential pathophysiologic mechanism highlights the role of IL-1, IL-6 and tumor necrosis factor-alpha (TNF-α) in the pathogenesis of aseptic meningitis in FMF and CINCA syndrome." (PMID 32765981, 2020). "We will discuss the emerging role of proinflammatory cytokines, such as interleukin 1 (IL-1), interleukin 6 (IL-6) and tumor necrosis factor-alpha (TNF-α), in the pathogenesis of aseptic meningitis in ADs, and will explore recent treatment developments, such as the use of biological agents." (PMID 32765981, 2020).
Atherosclerotic lesion (6 papers, 2017 to 2025). A lesion associated with atherosclerosis, a multifactorial and multipart progressive disease manifested by the focal development within the arterial wall of lesions, that ranges from the development of a fatty streak, plaque progression, and plaque disruption. "Given that NaVO3 induced atherosclerotic lesions and VSMC phenotype alternation accompanied by increasing plasma IL-6 levels, we wondered if IL-6 secreted by VSMCs may be involved in vanadium salt-induced VSMC migration and proliferation." (PMID 31817202, 2019).
atopic asthma (6 papers, 2012 to 2020). An asthma that is characterized by symptoms that are triggered by an allergic reaction caused by inhaled allergens such as dust mite allergen, pet dander, pollen and mold. "Multivariate analysis further identified an association between IL-6 production, residence location and atopic asthma (p for interaction = 0.03) – a notable finding given the extensive literature on urban-rural differences in inflammatory disease." (PMID 22685596, 2012). "More generally, our results, taken together with those from previous studies, suggest that IL-6 signaling plays a role in allergic inflammation, potentially contributing to the development of atopic asthma phenotypes and other allergy-related diseases." (PMID 28334838, 2017). "IL-6 production was significantly increased in urban children and tended to be higher in FN children and children with atopic asthma." (PMID 22685596, 2012). "The effect of SES trajectories on IL-6 production was found to be independent of FN ethnicity, residence location, atopic asthma, and family size." (PMID 22685596, 2012).
autoinflammatory syndrome (6 papers, 2014 to 2022). A group of disorders of the innate immune system characterized by attacks of seemingly unprovoked inflammation without significant levels of either autoantibodies or autoreactive T cells more characteristic of autoimmune disease. "Specifically, TNF-α induces the production of IL-1β and IL-6, with the former being a crucial mediator of the inflammatory response, causing various autoinflammatory syndromes, and the latter being secreted by T cells and macrophages to stimulate the immune response." (PMID 27382402, 2016). "That analysis identified 3 factors, IL-6, IL-17, and Stat3, that may serve as therapeutic targets in treatment of auto-inflammatory syndromes." (PMID 30361689, 2018). "Taking into account the clinical picture, the lack of female preponderance, the lack of HLA class II associations, the general lack of autoantibodies in this disease phase and an excellent response to IL-1 and IL-6 blockade, sJIA may well be regarded as a 'pure’ autoinflammatory syndrome." (PMID 25114627, 2014).
babesiosis (6 papers, 2016 to 2025). Babesiosis refers to a condition caused by microscopic parasites that infect the red blood cells. "Furthermore, IL-6 and IL-4 play a pathogenic role in the persistence of Babesia infections through the inhibition of protective IFN-γ." (PMID 29312230, 2017). "Notably, several studies have found that babesiosis or malaria infections can lead to decreased thyroid function, which may be associated with increased IL-6 concentrations." (PMID 39716228, 2024). "Nuclear factor kappa-light-chain-enhancer of activated B cells (NF-κB) activation drives the release of pro-inflammatory molecules, such as IL-6, TNF-alpha, ICAM-1, and IL-8, previously associated with babesiosis." (PMID 40305281, 2025). "IL-6 and IL-10 support the secretion of Th2 cells, which simultaneously activate B cells to induce systemic immune responses and produce antibodies to protect against Babesia infections." (PMID 29312230, 2017). "The data indicate that IL-6 and IL-4 may play a key role in protecting mice from Babesia infection." (PMID 29312230, 2017). "In our study concentrations for CRP and SAA were significantly increased in the Babesia-infected group, indicating that IL-6 is associated with an inflammatory state in babesiosis, despite the fact that concentrations were not significantly different from the control dogs." (PMID 26953797, 2016).
behavioral disorders (6 papers, 2018 to 2023). "This suggests that inhibition of excessive production of IL-6 in the CA2 region of the hippocampus following FS may be effective in treating ASD-like behavioral disorders." (PMID 37887290, 2023). "Children with externalizing behavioral problems have elevated levels of C-reactive protein (CRP) and interleukin 6 (IL-6)." (PMID 37783687, 2023). "Although in our cohort (composed of 50.8% female, with a range of 3–6 years), we do not observe differences in the IL-6 levels due to gender or age, the results demonstrate that IL-6 levels are higher in saliva samples from children’s with behavior problems." (PMID 36225733, 2022).
blastomycosis (6 papers, 2019 to 2024). Blastomycosis is a rare infection that may develop when people inhale a fungus called Blastomyces dermatitidis, a fungus that is found in moist soil, particularly where there is rotting vegetation. "Genetic predisposition may significantly influence vulnerability to blastomycosis, as a study has identified interleukin-6 as a potential susceptibility locus." (PMID 39469362, 2024). "Genetic variation in IL-6 results in blastomycosis, and defect in IL-10 and IL-6 signaling affects STAT3, a key immune response molecule." (PMID 34490039, 2021). "Recently a genome-wide analysis of seven Hmong patients with clinically significant blastomycosis identified 25 polymorphisms in proximity to the IL-6 gene or AS-IL6, a long non-coding RNA that was recently reported to be involved in IL-6 production." (PMID 32545735, 2020).
bone marrow failure (6 papers, 2013 to 2024). "As insufficient GM-CSF signaling caused pulmonary alveolar proteinosis and excessive IL-6 signaling promoted bone marrow failure and GATA2 deficiency patient phenotypes, these results provide insight into mechanisms underlying GATA2-linked pathologies." (PMID 36809258, 2023). "Higher level of IL-6 was considered to be related to bone marrow failure and the high risk of relapse for AML." (PMID 36685973, 2022). "Lacking miR-146a, the action of NF-κB is extended, the production of IL-6 is exaggerated, the myelopoietic stress on the HSPCs is extended, and the over time the pathological symptoms of continual myelopoiesis, bone marrow failure, and cancer emerge." (PMID 23705069, 2013). "Ectopic IL-6 signaling drives immune dysregulation and bone marrow failure." (PMID 36809258, 2023). "While anti-IL-6 therapies can reduce corticosteroid doses and help control inflammatory symptoms in some patients with VEXAS, a significant number still experience progressive bone marrow failure." (PMID 39598114, 2024).
Bradycardia (6 papers, 2019 to 2025). A slower than normal heart rate (in adults, slower than 60 beats per minute). "The mechanisms by which bradyarrhythmias occur are not yet completely known but a strong association between Interleukin-6 and bradycardia has been documented." (PMID 40564087, 2025). "IL-6 combined with AZM and HCQ (0.5-time CRD) or HCQ (1-time CRD) or HCQ (2-time CRD) caused further significant and dose-dependent bradycardia, PR, QRS and QTc prolongations, and complete atrioventricular dissociation." (PMID 35058480, 2022). "Their study proposes that IL-6 microinjection has been reported to have attenuated L-glutamate-induced bradycardia in the NTS." (PMID 32532282, 2020). "However, we observed marked bradycardia, followed by a complete atrioventricular dissociation, heart block, and asystole in guinea pigs challenged with in vivo applications of IL-6-sIL-6R-IL-18, suggesting an involvement of a decrease in peak INa." (PMID 39063055, 2024). "Furthermore, many patients with bradycardia received IL-6 inhibitors and hemoperfusion as rescue therapy." (PMID 35888669, 2022). "In addition, a greater proportion of patients with bradycardia received interleukin-6 inhibitors and hemoperfusion as a rescue therapy than those with non-bradycardia." (PMID 35888669, 2022).
brain cancer (6 papers, 2017 to 2024). A primary or metastatic malignant neoplasm affecting the brain. "Evidently, IL6 has an important association with brain cancer development." (PMID 28346397, 2017). "IL-6 is another cytokine frequently elevated in different brain cancers and involved in modulation of immune responses." (PMID 28346397, 2017). "In brain cancer studies, a strong correlation was observed among NF-κB activation, IL-6 overexpression, and poor patient survival." (PMID 28346397, 2017). "Radiotherapy of brain cancer is known to induce acute and late pro-inflammatory reactions that involve the production of several cytokines (e.g., TNF-α, IL-1, IL-6, IL-8, IFN-γ), many of which are potent inducers of kinin B1R/B2R expression." (PMID 33003415, 2020).
breast adenocarcinoma (6 papers, 2015 to 2018). "Xian-Peng reported that IL-6 was responsible for maintaining the growth of human breast adenocarcinoma cell line MCF-7 when cultured with human IL-6 and IL-6 soluble receptor." (PMID 30648081, 2018). "Ectopic stable IL-6 expressing MCF-7 breast adenocarcinoma cells exhibited an EMT phenotype characterized by impaired E-cadherin expression and induction of Vimentin, N-cadherin, Snail, and Twist." (PMID 30083161, 2018). "Next, we used T47D cells, a human breast adenocarcinoma cell line which lacks constitutively active Stat but is biologically responsive to GH and IL6 which are activators of Stat5 and Stat3 signaling pathway, respectively." (PMID 27557509, 2017). "Next, the effect of MNP anti-IL6 siRNA on hepatic thermal ablation was assessed in a second subcutaneous tumor model (MATBIII rat breast adenocarcinoma line) at 3.5d post-treatment (due to the relatively faster innate tumor growth rate, all tumors reached the mandated size for sacrifice after 3.5d)." (PMID 26154425, 2015). "Breast adenocarcinoma MCF7 cells have low levels of pSTAT3, while MDA-MB-468 cells express high basal levels of pSTAT3 and have also been shown to auto-secrete IL6." (PMID 28636670, 2017). "To analyze whether NPQ-C6 was also able to downregulate cytokine-induced STAT5/3 activities, we used a human breast adenocarcinoma cell line (T47D) which fails constitutively active STAT but is able to respond to GH and IL6, which are activators of STAT5 and STAT3 signaling pathway, respectively." (PMID 30687103, 2018).
capillary leak syndrome (6 papers, 2016 to 2025). A syndrome characterized by leakage of intravascular fluids into the extravascular space. "IL-6 is a key mediator, contributing to fever, capillary leak syndrome, and hypotension." (PMID 40277755, 2025). "Moreover, increased secretion of interleukin-6 activates vascular endothelial growth factor, reduces the expression of E-cadherin, and enhances vascular permeability, resulting in capillary leak syndrome." (PMID 37795409, 2023). "Capillary leak syndrome (CLS) has also been correlated with hypotension and is like CRS in that IL-6 is a common cytokine that is released in CLS which pertains to cardiomyopathy." (PMID 41018125, 2025).
Chagas cardiomyopathy (6 papers, 2010 to 2025). A disease of the cardiac muscle developed subsequent to the initial protozoan infection by trypanosoma cruzi. "Research suggests that individuals at high risk of sudden death in Chagas cardiomyopathy exhibit elevated serum levels of IFN-γ, TNF-α, IL-6, IL-2, IL-10, and IL-4 compared to those at low risk." (PMID 39907396, 2025). "Our study also aimed to assess the plasmatic levels of TNFα, IL6 andendothelin 1, in patients with different clinical forms of Chagas cardiomyopathy.These biomarkers have been described to be elevated in Chagas cardiomyopathy." (PMID 20877635, 2010). "Indeed, cytokines such as interleukin (IL)-1 and IL-6, which are present at high levels during acute Chagas cardiomyopathy, also induce VEGF production." (PMID 36417626, 2022). "The individuals with an indeterminate state had higher IL-10 expression, whereas the Chagas cardiomyopathy group presented the highest inflammatory cytokine expression (IFN-γ, TNF-α, IL-6 and IL-1β)." (PMID 38133693, 2023).
chordoma (6 papers, 2020 to 2026). Chordomas are rare malignant tumors arising from embryonic remnants of the notochord in axial skeleton. "Previous studies suggested that some cytokines and chemokines, including TNFα, LIF, IL-6 and IL-8 played important roles in the immune microenvironment of chordoma, but relatively few studies had been conducted." (PMID 38983929, 2024). "Interesting, several cytokines including interleukin-6 and tumor necrosis factor-alpha were reported to be elevated in chordoma patients, suggesting the potential role of cytokines in chordoma progression." (PMID 33046024, 2020). "Our findings align with previous research on miRNA–cytokine networks in spinal disorders, including miR-17 regulation of TNF-α and IL-6 in LDDD and TNF-α–mediated progression in chordomas." (PMID 41535614, 2026). "Recently, it had been discovered that kinds of cytokines and chemokines, such as TGFβ, TNFα, CCL5, IL-8, IL-6 and LIF, also as important mediators of cellular interactions, had been found to be highly expressed in chordomas and play important roles in the immune microenvironment." (PMID 38983929, 2024). "In line with the observations in cell lines, MSigDB enrichment scores revealed that interferon alpha and gamma response, inflammatory response, and IL6/JAK/STAT3 and IL2/STAT5 signaling were among the most enriched signaling axes in chordoma but not in the pan-cancer cohort." (PMID 40901948, 2025).